ENSG00000269590 (novel protein)
Gene: Protein-coding gene on chromosome 19 (12,664,828 to 12,669,397, reverse strand). Ensembl gene ENSG00000269590.
Genetic constraint (gnomAD): Loss-of-function variants: 19 observed, 24.55 expected, observed/expected ratio (o/e) 0.77, 90% interval 0.54 to 1.13. Missense variants: 244 observed, 282.24 expected, observed/expected ratio (o/e) 0.86, 90% interval 0.78 to 0.96. Synonymous variants: 108 observed, 109.65 expected, observed/expected ratio (o/e) 0.98, 90% interval 0.84 to 1.16.